XPO1 (exportin 1)
Diseases named in the same sentence as XPO1 in open-access papers (continued):
Sharing a sentence is not in itself a finding about the gene and the disease.
breast carcinoma (35 papers, 2014 to 2025). "In particular CRM1/XPO1 overexpression in breast cancer tumors is associated to poor prognostic characteristics including larger tumor size and positive lymph node metastasis." (PMID 33117284, 2020). "Similarly, changes in the expression levels of proteins that affect the nucleocytoplasmic translocation of ERα such as CRM1/XPO1 or prosaposin have also been linked to breast cancer development." (PMID 33117284, 2020). "Screening across breast cancer cell lines from the CTRPv2 dataset (n = 40), we evaluated all compounds (n = 481) in combination with leptomycin B, an XPO1 inhibitor." (PMID 41155531, 2025). "IDACombo identified parthenolide as the top candidate to be combined with XPO1 inhibitor in breast cancer from a total of 481 agents screened." (PMID 41155531, 2025). "Similar patterns of XPO1 mRNA expression were observed in both clinical studies with the basal-like breast cancer subtype having the highest and normal-like subtype having the lowest expression levels." (PMID 39682167, 2024). "Student t-test results indicate that the expression levels of XPO1 were statistically significant in basal-like breast cancer compared to any other breast cancer subtype or normal tissue." (PMID 39682167, 2024). "We first examined the drug target, namely the XPO1 gene expression levels by breast cancer subtype across the patient samples in METABRIC and TCGA." (PMID 39682167, 2024). "Compared to normal tissue controls, however, the relocation of E2F7, but not E2F1, from the nucleus to the cytoplasm is induced by the overexpressed XPO1, and is commonly observed in colorectal cancer, prostate cancer, breast cancer, and HNSCC." (PMID 35197448, 2022). "Across all TCGA samples, XPO1 was, on average, significantly overexpressed in TCGA breast cancer patient samples compared to adjacent normal tissue." (PMID 34628286, 2021). "Inhibition of XPO1 decreased phosphorylation of AKT (ser473) in tamoxifen-resistant breast cancer cells MCF-7 and tumor xenografts." (PMID 34384466, 2021). "Using the Seahorse metabolic profiler, we showed that ERα-XPO1 targeting changed the metabolic phenotype of TAM-resistant breast cancer cells from an energetic to a quiescent profile." (PMID 30987380, 2019). "To validate our results, we performed IHC analysis for XPO1 protein expression in two independent breast tumor sets with samples from various breast cancer subtypes." (PMID 30987380, 2019). "Our studies provide a novel mechanism of action of combined targeting of ERα and XPO1 to overcome TAM resistance in recurrent ERα (+) breast cancer." (PMID 30987380, 2019). "To assess the effects of selinexor on XPO1 expression, we chose an array of breast cancer cell lines representing varying hormone receptor status and representing different levels of sensitivity to selinexor." (PMID 28810913, 2017). "In MCF-7 breast cancer cell line, the transcription of this region leads to a longer transcript, approximately of 2,200nt, thus overlapping the third exon of XPO1 gene." (PMID 27447964, 2017). "XPO1 mediates nuclear export of several proteins that have been linked to TNBC, and there have been efforts to show breast cancer growth inhibition by several selective inhibitors of nuclear export." (PMID 28810913, 2017). "Lymphoid derived Jurkat cells are more sensitive to XPO1 inhibition by SINE than Raji cells while the breast cancer cells T47D are more resistant than HCC1937 cells." (PMID 26991404, 2016). "In order to validate an XPO1 inhibition-mediated mechanism of action, MCF-7 breast cancer cells were transfected with wild-type or mut-cys528 XPO1 constructs followed by SINE treatment." (PMID 26536918, 2015). "XPO1 and NUP214, two associated proteins whose regulatory targets are mutually upregulated in high-ColX module tumors, have collectively been described as drivers of breast cancer and markers of poor survival in pancreatic cancer." (PMID 39939916, 2025).
breast carcinoma (continued). "Furthermore, XPO1 has been reported to be highly expressed in various tumors including breast cancer, making it a promising therapeutic target." (PMID 41155531, 2025). "By utilizing a computational drug repurposing approach, XPO1 inhibitors were identified to be preferentially sensitive in TNBC compared to other breast cancer subtypes and its efficacy validated in an independent patient dataset and across various TNBC cell lines." (PMID 39682167, 2024). "Using publicly available XPO1 expression data and leptomycin B sensitivity information in a collection of breast cancer cell lines from the CCLE and CTRPv2, we performed a correlation analysis between XPO1 expression (at mRNA and protein level) and measured the cellular sensitivity to leptomycin B." (PMID 39682167, 2024). "Since Akt is a major regulator of cell metabolism and TAM responsiveness, we hypothesized that XPO1 modulates Akt activity to rewire metabolism and provide new survival/escape routes to breast cancer cells." (PMID 30987380, 2019). "Therefore, XPO1 could be an excellent therapeutic target in breast cancer as XPO1 is already targeted in other therapy-resistant cancers with the highly specific small molecule inhibitor SEL, which is an orally active and well-tolerated drug." (PMID 30987380, 2019). "A study examined the synergistic anticancer potential of the isothiazolonaphthoquinone-based compound 57, an activator of FOXO nuclear–cytoplasmic shuttling, in combination with selinexor, an exportin-1 (XPO1) inhibitor, against breast cancer." (PMID 41471376, 2025). "Consistently, the mRNA expression levels of XPO1 and KLF5 are positively correlated in breast cancer clinical samples, particularly in BLBC patients." (PMID 39888288, 2025). "In this respect, neurofibromin has previously been reported within the nucleus of neurons and glia, as well as in the nucleus of breast cancer cells, as a result of interactions with Ran and CRM-1 (also known as XPO1)." (PMID 35188187, 2022). "As presented here, these pre-clinical studies suggest that co-targeting XPO1 and PI3K/mTOR is a promising approach for the treatment of basal-like breast cancer." (PMID 34628286, 2021). "exportin-1 inhibition with the selinexor analogue KPT-276 has been shown to repress STAT3 activation and survivin transcription in breast cancer cell lines." (PMID 32231398, 2020). "Breast cancer tissue arrays were stained with anti-ARRDC3, anti-XPO1, and anti-ITG β4 antibodies for immunohistochemistry analysis." (PMID 28881784, 2017). "Our rationale is that targeting XPO1 together with ERα is clinically relevant and combining TAM with SEL potentially offers higher efficacy, specificity, and lower toxicity for the treatment of endocrine resistant, recurrent ER (+) breast cancer." (PMID 30987380, 2019). "To investigate the mechanisms of XPO1 inhibition that overcome the resistance to CYH33 in breast cancer cells, we examined the expression profiles of MCF7R and parental cells upon treatment with KPT-330, one of the most advanced XPO1 inhibitors, with a gene-expression microarray." (PMID 31798976, 2019). "STAT3 has been identified as XPO1 cargo in breast cancer, and although it has not yet been validated in lymphoma, its importance in immune cell maturation and activation and presence of a bona fide XPO1 binding NES suggests that it is most likely an XPO1 cargo molecule in NHL." (PMID 36671496, 2023). "Therefore, preclinical studies of XPO1 inhibition using SINE compounds may lead to a novel treatment for various types of cancer, including breast cancer." (PMID 38938904, 2022).
breast carcinoma (continued). "In combination, these results indicate that ISG12 promotes the interaction of ERα with the nuclear exportin CRM1/XPO1 and suggest that the ISG12-dependent down-regulation of ERα transactivation may be mediated by its export from the nucleus in breast cancer cells." (PMID 33117284, 2020). "Since cancer cells of different tumor types have been shown to be more sensitive to XPO1 inhibition than normal cells, combining TAM with SEL potentially offers higher efficacy, specificity and lower toxicity for treatment of endocrine resistant, recurrent ER (+) breast cancer." (PMID 30987380, 2019). "However, it is not known whether XPO1 activates other mechanisms that may be targeted by therapies in current use, specifically for endocrine therapy resistant and ER (+) breast cancers." (PMID 30987380, 2019).
leukemia (32 papers, 2015 to 2025). A malignant (clonal) hematologic disorder, involving hematopoietic stem cells and characterized by the presence of primitive or atypical myeloid or lymphoid cells in the bone marrow and the blood. "By inhibiting the function of XPO1, it restores the activity of tumor suppressor proteins, thereby enhancing the anti-leukemia effect." (PMID 40463909, 2025). "In summary, XPO1 inhibition by eltanexor eradicated primary human DEK::NUP214 leukemia cells in vivo and proved an exceptional on-target sensitivity of these cells in a primary human AML model." (PMID 40148556, 2025). "In summary, XPO1 stabilizes DN at chromatin to allow the activation of its oncogenic gene signature, while targeting XPO1 treats leukemia successfully in vivo." (PMID 40148556, 2025). "Altogether, these results identified a novel function of DEK::NUP214 as an XPO1-dependent transcriptional activator of key leukemia drivers and provide a rationale to explore the use of XPO1 inhibitors in this patient population." (PMID 40204893, 2025). "Reported studies have shown increased expression of XPO1 in various types of cancer, including pancreatic, ovarian, glioma, lung, gastric, prostate, liver, cervical, multiple myeloid, leukemia, and colorectal cancers." (PMID 39177040, 2024). "Selinexor is an oral, first-in-class, selective inhibitor of nuclear export compound, which blocks XPO1 function and has shown promising anti-leukemia activity in vitro and in vivo." (PMID 37601075, 2023). "Selinexor was FDA-approved in 2019 for treating lymphomas and leukemia by covalently inhibiting the highly activated nuclear export receptor, exportin 1 (XPO1)." (PMID 36558928, 2022). "In leukemia and solid tumors, XPO1 is overexpressed leading to enhanced transport of these proteins to the cytoplasm, thereby neutralizing their anti-neoplastic functions and functionally inactivating TSP/GRP." (PMID 29304833, 2018). "This same explanation, however, implies the E571 XPO1 mutation in B lymphocytes alone is not sufficient to spur development of an overt leukemia, as very few CLL patients presented with a low VAF at the time of diagnosis." (PMID 33451349, 2021). "With respect to EMB (XPO1 in mammals) and RAE1, their mammalian homologs have been shown to contribute to NA9-induced leukemia through their association with the FG / GLFG motifs and GLEBS domain of NA9, respectively, which appears to interfere with nucleocytoplasmic transport." (PMID 34383740, 2021). "Biologically, this report reinforces the concept of NPM1 as ‘born-to be-exported’ in NPM1-mutated AML, meaning that only those mutations that lead to exportin-1(XPO1)/NPM1 mutant interaction and the following dislocation of NPM1 in the cell cytoplasm are selected to develop leukemia." (PMID 34573408, 2021). "While amplified copy number may explain the XPO1 overexpression in some leukemia and lymphoma subtypes, for the majority of human cancers, the mechanism of XPO1 overexpression remains unknown." (PMID 32487143, 2020). "Chromatin binding of XPO1 has also been shown in NPM1c and SET::NUP214 leukemia, suggesting that XPO1 mediates and stabilizes chromatin binding of DN." (PMID 40148556, 2025). "Among the small molecules that inhibit exportin-1 function, selinexor (KPT-330) is under clinical trials for most cancer types, including leukemia, and lung, prostate, gastric, breast, ovarian, and cervical cancers." (PMID 32825184, 2020). "Selinexor, an exportin 1 (XPO1/CRM1) inhibitor, has demonstrated anti-leukemia activity as a single agent, as well as in combination with anthracyclines and/or DNA-damaging agents." (PMID 29304833, 2018). "In addition, XPO1 was also overexpressed compared to PBMC, normal B and T cells at the protein, as well as mRNA level in a human lymphoma/leukemia study." (PMID 40872651, 2025).
leukemia (continued). "We confirmed these findings in leukaemia cells; treatment with both leptomycin and selinexor increased the levels of nuclear HK2, demonstrating that the nuclear export of HK2 requires exportin 1 (XPO1, also known as CRM1)." (PMID 35668135, 2022). "Sixty-nine of the 71 evaluated leukemia-cell samples (97%) had a low-programmed (LP-CLL) epigenetic signature; in contrast, only 578 of the 1100 cases (53%) without detectable XPO1 mutations had such an epigenetic signature." (PMID 33451349, 2021). "HL-60, Jurkat and K-562 leukemia cells were co-transfected with plasmids expressing Cas9-NLS and an XPO1 targeting single guide RNA together with a 135 bases single-stranded oligodeoxynucleotide repair donor template containing the TGT to TCA mutation in addition to 3 silent mutations." (PMID 27634897, 2016). "We first validated the expression of the DEK::NUP214 and XPO1 genes and proteins in the FKH-1 cell line, using established leukemia cell lines as the negative control." (PMID 40148556, 2025). "The protein levels of XPO1 appears not apparently upregulated in HCMV infection at indicated time points, unlike in leukemia and other cancers." (PMID 34012430, 2021).
lymphoma (31 papers, 2015 to 2025). A malignant (clonal) proliferation of B- lymphocytes or T- lymphocytes which involves the lymph nodes, bone marrow and/or extranodal sites. "This central positioning within critical oncogenic networks underscores the clinical significance of detecting XPO1 mutations in lymphoma diagnosis and monitoring." (PMID 40806458, 2025). "XPO1 mutation renders lymphoma cells more sensitive to selinexor due to a faster degradation of mutant XPO1 compared to the wild‐type." (PMID 36727672, 2023). "Therefore, the cause of overexpression of XPO1 in the canine lymphoma cell lines observed in this study needs to be clarified in future studies." (PMID 40872651, 2025). "Given XPO1’s integral role in these interconnected oncogenic pathways and its interactions with established tumor suppressors and oncogenes, the detection of XPO1 mutations represents a crucial component of comprehensive lymphoma molecular profiling." (PMID 40806458, 2025). "KEGG pathway analysis revealed that XPO1 is associated with key lymphoma-related pathways, including the pathway in cancer, the PI3K-Akt signaling pathway, and the JAK-STAT signaling pathway, all of which regulate cancer cell survival, proliferation, and immune evasion." (PMID 40806458, 2025). "KEGG pathway analysis revealed that XPO1 is associated with key lymphoma-related pathways, including the pathway in cancer, the PI3K-Akt signaling pathway, and the JAK-STAT signaling pathway, all of which are fundamental regulators of cancer cell survival, proliferation, and immune evasion." (PMID 40806458, 2025). "In addition to overexpression, XPO1 mutations have been found in 0.5–2.9% of solid and hematopoietic tumors, with the highest incidence in lymphomas." (PMID 32487143, 2020). "A previous report described studies indicating that germline insertion of the E571K XPO1 mutation could accelerate development of lymphoma in mice made to express high-level c-Myc and BCL-2, suggesting such XPO1 mutations could contribute to oncogenic transformation." (PMID 33451349, 2021). "Leukemia and lymphoma cells with E571K mutations have increased sensitivity to selinexor in vitro, suggesting that upfront screening for mutations may have utility for precision medicine approaches utilizing XPO1-based management strategies." (PMID 34944778, 2021). "The expression levels of XPO1 mRNA and protein were well correlated between canine lymphoma cell lines." (PMID 40872651, 2025). "Western blot analysis was conducted to investigate the expression of the XPO1 protein in the canine lymphoma cell lines and the PBMCs as normal control, as well as a Raji cell line as a positive control." (PMID 40872651, 2025). "We evaluated the XPO1 gene expression in the eight canine lymphoma cell lines, including three B-cell lines (17-71, CLBL-1, and GL-1) and five T-cell lines (CLC, CLGL-90, Ema, Nody-1, and UL-1) as well as PBMCs obtained from a healthy dog." (PMID 40872651, 2025). "GO analysis further demonstrated that XPO1 is involved in critical biological processes essential for lymphoma progression." (PMID 40806458, 2025). "This in vitro study aimed to evaluate the XPO1 mRNA and protein expression in canine lymphoma cell lines and confirm the relevance with KPT-335." (PMID 40872651, 2025). "The expression of XPO1 protein in the PBMCs was less expressed when compared to those of the canine lymphoma cell lines." (PMID 40872651, 2025). "Correspondingly, GO analysis further demonstrated XPO1’s participation in essential biological processes that reinforce its pivotal role in lymphoma progression." (PMID 40806458, 2025).